PANX2 (pannexin 2)
Diseases named in the same sentence as PANX2 in open-access papers (continued):
Sharing a sentence is not in itself a finding about the gene and the disease.
tumor (17 papers, 2014 to 2026). "Nu-PANX2 was significantly associated with sex (P = 0.009), tumor size (P = 0.001), tumor stage (P < 0.001), and tumor necrosis (P = 0.003)." (PMID 30723706, 2019). "Cy-PANX2 was significantly associated with age of patients (P = 0.032), tumor size (P < 0.001), tumor stage (P < 0.001), lymph node metastasis (P = 0.018), nuclear grade (P = 0.006), and tumor necrosis (P = 0.011)." (PMID 30723706, 2019). "In addition, Panx1 and Panx2 expression were associated with reduced tumor volume in murine C6 tumor implants, which led to propose them as tumor suppressor genes." (PMID 25018732, 2014). "Clinically, PANX2 expression is downregulated during tumor progression, and low PANX2 levels correlate with poor prognosis." (PMID 42210821, 2026). "Collectively, our findings establish PANX2 as a tumor suppressor linking disulfidptosis to antitumor immunity, offering a dual-target strategy for LUAD therapy." (PMID 42210821, 2026). "In humanized mouse models, PANX2 overexpression suppresses tumor growth-effects reversed by NRF2 knockdown, G6PD overexpression, or P2X7R blockade." (PMID 42210821, 2026). "After analyzing numerous clinical variables such as tumor type and radiation treatment, a model that predicted the possible outcome of a patient was created based on the varying levels of PANX2 in patients." (PMID 37241023, 2023). "When compared to PANX2′s involvement in oncogenicity, High Throughput cDNA microanalysis showed that PANX2 acted similarly to tumor suppressor genes due to the reduction of tumor cells when PANX2 was restored to normal levels." (PMID 37241023, 2023). "One experimental study analyzed the connection between PANX2 and cancer immune infiltrates using a technique called Tumor Immune Estimate Resource using NIH’s data portal." (PMID 37241023, 2023). "PANX2 is functionally known for its potential to create gap junctions that facilitate ion exchange between cells and their role as a potential tumor suppressor in the human brain, skin, and liver tissues." (PMID 35630307, 2022). "Panx2 localization at ER-mitochondria contact sites likely contributes to its tumor-suppressing properties." (PMID 30862038, 2019). "In this study, we investigate the localization of pannexin 2 (Panx2), a membrane channel protein showing tumor-suppressing properties in cancer cells." (PMID 30862038, 2019). "In CCRCCs, immunohistochemical expression of FAM83H and PANX2 was seen in both the cytoplasm and nuclei of tumor cells." (PMID 30723706, 2019). "Over-expressed Panx2-HA or -GFP tagged proteins had a significant reduction in in vivo tumour growth in nude mice when compared to controls." (PMID 27229305, 2016). "Here, we identify Pannexin 2 (PANX2) as a tumor suppressor in LUAD." (PMID 42210821, 2026). "GPR156 and PANX2 protein levels were increased in tumor tissues, consistent with their mRNA levels." (PMID 36465397, 2022). "Mechanistically, a large number of biomolecules and tumor-associated signaling pathways, including DECR1, PANX2, HSPB1, ACOT8, SUV39H1, NCOA4, PI3K-AKT-mTOR signaling, VHL/HIF-2α pathway, and Hippo/TAZ signaling pathway, have been reported to regulate ferroptosis in urologic cancers." (PMID 34922551, 2021). "Interestingly, we recently showed that Panx2, a gap junction with tumor-suppressing properties, forms puncta that localize to unidentified cytoplasmic compartments in mammalian cells." (PMID 30862038, 2019). "Additionally, in Kaplan-Meier survival plots of differential expression of Panx2 in human tumour samples, there was a positive correlation between Panx2 expression and patient survival." (PMID 27229305, 2016). "And overexpressed Panx2 could prevent tumor cells from killing by 5-FU." (PMID 40909173, 2025). "Contrastingly, Panx2 could also function as a potential tumor suppressor gene." (PMID 40909173, 2025).
tumor (continued). "This study investigated the expression and clinical significance of FAM83H and PANX2 expressions in CCRCC and showed that the expression patterns of FAM83H and PANX2 were significantly associated with advanced clinicopathologic factors of CCRCC such as tumor size and tumor stage." (PMID 30723706, 2019). "Mechanistically, blocking enzymes such as DECR1, PANX2 and GPX4 can inhibit tumor growth with universal implications in understanding both resistance and metabolic events." (PMID 33596934, 2021). "Therefore, the factors included in the multivariate analysis were sex, age, tumor size, tumor stage, LN metastasis, histologic nuclear grade, tumor necrosis, and the expression of Nu-FAM83H, Cy-FAM83H, Nu-PANX2, and Cy-PANX2." (PMID 30723706, 2019). "When we performed multivariate analysis with inclusion of sex, age, tumor size, tumor stage, LN metastasis, histologic nuclear grade, tumor necrosis, and co-expression patterns of Nu-FAM83H and Nu-PANX2, the Nu-FAM83H/Nu-PANX2 expression patterns were independent indicators of OS and RFS." (PMID 30723706, 2019).
cancer (7 papers, 2019 to 2023). A tumor composed of atypical neoplastic, often pleomorphic cells that invade other tissues. "Recent studies have demonstrated the significant roles of the Panx family, especially Panx2, in many diseases including cancer and neurological diseases." (PMID 36869038, 2023). "Therefore, despite limited reports on the role of PANX2 in human cancers, our results suggest PANX2 as a potential biologic marker of CCRCC." (PMID 30723706, 2019). "The patients with Nu-PANX2-positive CCRCC had a 3.186-fold (95% CI; 1.450–7.002) greater risk of cancer-related death and a 2.302-fold (95% CI; 1.180–4.492) greater risk of relapse or cancer-related death compared with the patients with Nu-PANX2-negative CCRCC." (PMID 30723706, 2019). "Functional data indicate that Panx2 over-expression sensitizes cancer cells to apoptotic signals." (PMID 30862038, 2019). "Therefore, further study is needed to clarify the role of PANX2 in human cancers." (PMID 30723706, 2019). "Although not highly researched, studies have shown that the role of PANX2 in ATP regulation during cancers might connect with the purinergic role of ATP in various neurological disorders." (PMID 37241023, 2023).
Cardiovascular Disease (2 papers, 2020 to 2026). "As such, future research into pannexin function in cardiovascular disease should not entirely rule out Panx2 and Panx3." (PMID 41569301, 2026).
neurologic disorders (2 papers, 2024 to 2025). "Although PANX2 has been identified to be associated with some neurological disorders, the function of PANX2 in the central nervous system is not fully understood, because PANX2 is located in the cellular chamber, which limits the evaluation of its channel function by electrophysiological methods." (PMID 37196132, 2024).
degenerative diseases (1 paper, 2024). "Given the involvement of the ER-mitochondria tethering complex in the regulation of calcium or lipid homeostasis, cell survival, apoptosis, and its importance in degenerative diseases, Panx2 is likely to exert significant effects in the musculoskeletal system." (PMID 38705887, 2024).
PANX2 also shares sentences with these, for which no sentence is quoted: astrocytoma (1 paper); brain injury (1); cholangiocarcinoma (1); glioblastoma multiforme (1); hearing loss (1); lung adenocarcinoma (1); lymph node metastasis (1); migraines (1); multiple sclerosis (1); myelodysplastic syndrome (1); myocardial infarction (1); renal cell carcinoma (1); testicular cancer (1).